LINC01998 (long independently transcribed non-coding RNA 1998)
Gene: Long non-coding RNA gene on chromosome 3 (150,077,494 to 150,080,121, reverse strand). Ensembl gene ENSG00000243321.
Gene Ontology:
Biological process: RNA processing
Cellular component: nucleolus